IL1A (interleukin 1 alpha)
Diseases named in the same sentence as IL1A in open-access papers (continued):
Sharing a sentence is not in itself a finding about the gene and the disease.
infection (continued). "While an early activation of interferon α/β signaling was observed, several innate immune signaling pathways including TLR, TNF, NF-κB, and NOD-like receptor signaling and key inflammatory cytokines such as Il-1α, Il-1β, and TNF typically activated following infection were suppressed." (PMID 32722194, 2020). "We show that microglia, not infiltrating macrophages, release IL-1α ex vivo in an infection-dependent and gasdermin-D-dependent manner." (PMID 32703941, 2020). "IL-1α, which was primarily produced by the JEV-infected peritoneal macrophages, was shown to be the key mediator that induced BBB breakdown and promoted JEV neuroinvasion at the early phase of infection." (PMID 32611752, 2020). "Consistent with results regarding immune cell and neutrophil numbers, the concentrations of IL-1α, IL-6, and IL-12 subunit p40 in BALF on day 1 post-Mp infection were significantly lower or tended to be lower in C57BL/6J, DBA/1, and CBA/N mice than in BALB/c mice." (PMID 33520736, 2020). "While some cytokines/chemokines such as TNFα and MIP-1β peaked very early after H5N1 infection (12 h), others, i.e. IL-1α and RANTES peaked somewhat later (at 30 h), followed by KC (neutrophil-activating protein-3) and IL-6, reaching their peak at 72 h after infection." (PMID 33362782, 2020). "There was higher IL-1α detected in non-CF AEC compared to CF AEC in response to RV infection suggesting IL-1α release from CF AEC occurs predominantly via necrotic cell death post-infection, and release from non-CF AEC via apoptotic cell death." (PMID 32328066, 2020). "Similar to the reduced levels of IL-8, levels of pro-inflammatory cytokines IL-1α,−1β,−4, and−6 as well as LCN2 were also reduced upon P4 ΔentA infection in mammary gland homogenates of both mouse strains compared with their P4-infected counterparts (P ≤ 0.08)." (PMID 33240956, 2020). "The release of other known candidalysin-induced proteins, such as hBD2, hBD3, LL37, G-CSF, GM-CSF, IL-1α and IL-1β, do not appear to be affected by Apyrase during infection." (PMID 32178483, 2020). "While IL-1α and IL-1β levels in WT and IL-1R−/− mice were similar, levels of IL-6, IL-12p70, IFN–γ, CCL2, CCL3, and CXCL9 were significantly lower in IL-1R−/− mice compared with wild-type mice following infection with P1/7 (p < 0.05)." (PMID 31262357, 2019). "Il1a−/− and C57BL/6 mice presented comparable initial body weights, suggesting that the food intake was similar for these mouse strains before infection." (PMID 31110285, 2019). "In addition corneal epithelial cell-derived interleukin-1 alpha (IL-1α) promotes the expression of ICAM-1 and VCAM-1 on endothelial cells following infection." (PMID 31540200, 2019). "We also recovered more fungal colonies in the lungs, but not livers of Il1a-/- animals after 15 days of infection." (PMID 31425553, 2019). "Both F4+ETEC and ETEC-derived flagellin are known to trigger the fast secretion of pro-inflammatory cytokines by porcine IECs at the early stage of infection, such as TNF-α, prostaglandin E2 (PGE2), IL-6, IL-8 and IL-1α, which are intended to disarm or destroy invading bacteria." (PMID 31221216, 2019). "Compared to those of mock infection or VR2332c, JA142c and poly I:C induced significantly increased transcript levels of IFN-β and pro-inflammatory cytokines (IL-1α, IL-1β, IL-6, IL-8, IL-12, and TNF-α) at either two or all three time points assayed (12, 24 and 36 hpi)." (PMID 30509265, 2018). "When the infection was mostly cleared in WT mice (day 9), we observed a decrease in most chemokines, but not in IL-1α and IL-1β, CCL7, and CCL4." (PMID 30102746, 2018). "IL-1α and TNF-α are also more abundant in the lungs of C57BL/6J mice, suggesting that wild-type but not C3–/– mice develop a fever response to infection that contributes to weight loss and respiratory dysfunction phenotypes." (PMID 30301856, 2018).
infection (continued). "Similar to airway epithelial cells, human macrophages express type I and type III IFNs, IL-1α, IL-1β, IL-6, TNF-α, CXCL8, CCL2 (MCP-1), CCL3 (MIP-1α), CCL4 (MIP1-β), CXCL9, and CXCL10 following infection with seasonal H1N1 or with H5N1, 2009 H1N1 strains demonstrating increased pathogenicity." (PMID 29623073, 2018). "Infection of MPI cells with HK bacteria resulted in the production of IL-6 and IL-1α from 24 h post-infection, in a MOI-dependent manner, while no IL-10 was detected (detection limit estimated to be ~60 pg/mL)." (PMID 29593716, 2018). "Compared with VR2332c or mock infection, JA142c induced increased levels of type I interferons and pro-inflammatory cytokines (TNF-α, IL-1α/β, IL-6, IL-8, and IL-12) in PAMs, and these elevated levels were comparable to the cytokine induction observed in PRRSV-challenged pigs." (PMID 30509265, 2018). "Thus, the early expression of IL-1α, particularly in the lungs of C57BL/6 mice on day 2 after infection, likely represents secreted IL-1α as a result of inflammasome activation." (PMID 30500862, 2018). "On one hand, proinflammatory cytokines (e.g., IL-1α, IL-2, and TNF-α) are necessary to initiate the inflammatory response during infection, but the overexpression of such cytokines may lead to pathological responses." (PMID 30627122, 2018). "Hence, we saw an increase in the inflammatory cytokines IL-1α and IL-1β and also MIG was increased in the early part of the infection in extracts from both strains of mice." (PMID 28235018, 2017). "IL-1α was also detected intracellularly and was significantly increased following HRV16 infection." (PMID 27583193, 2016). "These experiments demonstrate that appropriate innate IL-1α–IL-1R signaling is necessary for IAV clearance and at the same time instructs the formation of organized tertiary lymphoid tissues through induction of CXCL13 early after infection." (PMID 27579026, 2016). "The effect of PA01 infection on cell viability (data not shown) and IL‐1α release was compared to clinical isolates of P. aeruginosa (n = 7) grown from the airway samples of posttransplant patients." (PMID 26714197, 2016). "The molecules that depicted significant increases in those mAb treated-mice at 96 h after infection were CXCL1 (KC), CCL2 (MCP-1), CCL3 (MIP-1α), CCL4 (MIP-1β), CXCL2 (MIP-2), CXCL5 (LIX), IL-1α, IL-6, G-CSF, M-CSF, and TNF-α (for all, P < 0.01) and IL-1β, IL-15, IL-10, and LIF (for all, P < 0.05)." (PMID 27642235, 2016). "In aged mice, five markers were significantly elevated following infection, but these were not significant in young mice (IL-1α, IL-12(p40), IL-12(p70), MIP-1α, RANTES)." (PMID 27936166, 2016). "The signature also performed better than a wide range of host-proteins with an established role in the immune response to infection, including bacterial-related (e.g. TREM, IL-6 and IL-8), virus-related (e.g. IFN-γ and IL-2), and inflammation-related (e.g. IL-1a and TNF-α) proteins (P<10–8)." (PMID 25785720, 2015). "In contrast, mice lacking IL-1 receptor or IL-1β, but not IL-1α, appeared to control the infection in its early stages, but eventually succumbed." (PMID 25768794, 2015). "Although both cytokines are produced during infection with Ft LVS, Il-1b-/-, but not Il-1a-/-, mice were found to be more susceptible than C57BL/6J mice to Ft LVS infection." (PMID 25768794, 2015). "A detailed measurement of levels of 23 cytokines in the BAL, at 2-day intervals between days-0 to 25 revealed maximal elevation of inflammatory cytokines IL1a, IL1b, IL6, TNFα, IFNγas well as chemokines mKC, Eotaxin, MIP1a, MIP1b and MCP1 during the days 5–9 of infection (Fig-1A & Fig-S1)." (PMID 24505273, 2014). "Therefore, the effects of W. chondrophila infection upon the expression of the pro-inflammatory cytokines, TNF-α, IL-1α, IL-1β and the chemokine CXCL8 was investigated 24 h post-infection." (PMID 25010668, 2014).
infection (continued). "For the inflammatory response, nicotine could suppress the secretion of IL-1α, IL-4, IL-5, IL-10 and RANTES on day 6 and IL-17 on day 14 significantly after H9N2 infection compared with control mice." (PMID 24465940, 2014). "The IL-1RI-mediated deleterious role during B. thailandensis infection was due to the action of IL-1β, not IL-1α, although both cytokines are produced during infection." (PMID 25166912, 2014). "IL1α was not detectable until 24 h post infection at which point it was strongly inhibited by ERK inhibitor, but not by JNK alone, and the combined inhibitors suppressed production further." (PMID 25166426, 2014). "Treatment with IL-1Ra, and thereby blocking both IL-1α and IL-1β, led to increased viral titers in the initial phase of infection, whereas the absence of IL-1β alone did not affect viral replication." (PMID 24918427, 2014). "The products of the IL1A and IL1B genes are also involved in innate responses including up-regulation of endothelial adhesins for neutrophils, induction of acute-phase proteins, and early recruitment of inflammatory cells to the sites of infection." (PMID 23690962, 2013). "Further, in view of the persistent lung inflammation in single IL-1α or IL-1β deficient mice during chronic M. tuberculosis infection, we asked how the absence of IL-1α and/or IL-1β modulated the immune response in the lung after 1–3 months of infection." (PMID 25400917, 2013). "Expression of the pro-inflammatory Il-1a was only elevated in lethally infected mice at early, but not at late, stages of infection." (PMID 23526993, 2013). "The other 4 cytokines (TNF-α, IL-1α, IL-1β, and eotaxin) were elevated in non-surviving infected mice only at 48 hours after infection." (PMID 23520553, 2013). "In the present study, we have shown that IL-1α, IL-1β and IL-18 were released by NHBE cells following HRV14 infection, and that endogenous IL-1 signaling was essential for the induction and production of a number of pro-inflammatory mediators in response to the virus." (PMID 23723976, 2013). "We next sought to determine whether IL-1α is also released independently of ASC and NLRC4 during in vivo infection." (PMID 23762026, 2013). "In C57BL/6 mice, fetal infection did not affect the expression of IL-1α or S100A8 in U. parvum infected placentas." (PMID 22952869, 2012). "Both EV71 and CVA16 caused significant increases in IL-6 and RANTES mRNA levels; on the other hand, IL-10, NF-κB p65 and IL-1α were not elevated in RD cells 8 h after infection." (PMID 22666293, 2012). "Infection of mice with HP H5N1 or pandemic 1918 H1N1 influenza virus led to the rapid infiltration of macrophages and neutrophils into the lungs, resulting in the acute inflammation with the production of inflammatory cytokines such as IL-1α, IL-6 and INF-γ." (PMID 21592354, 2011). "For example, genes encoding several innate immune receptors and chemokines (such as TLR4, CD83, CCL2, CXCR4, CXCL5, IL1A and IL8)—several of which participate in the initiation of a T cell response during infection —showed increased relative expression in the BTB animal group." (PMID 22182502, 2011). "Interestingly, IL-1α and MIP-2 showed a reversal in the predominant trend, as these factors decreased through the course of infection." (PMID 20846417, 2010). "However, this is where the similarities end: Both NTHi WCL and IL-1α signal through entirely different sets of downstream players, possibly leading to a synergistic induction of HBD-2 in infection." (PMID 18578886, 2008). "The expression patterns of other cytokines shows that both disease forms have an inflammatory aetiology but that the central role for IL-1α in bovine paratuberculosis is not seen in the sheep infection." (PMID 17697353, 2007).
infection (continued). "However, indicating a broader inflammatory response in the whole brain, transcripts encoding pro-inflammatory cytokines, such as interleukin-1α (IL-1α), interleukin-6 (IL-6), interleukin-8 (IL8/CXCL1), and especially MCP1/CCL2, exhibited significant upregulation at 2- or 4-days post-infection." (PMID 40365287, 2025). "IL-1α and IL-1β were not detectable in the uninfected A-431 cells; induction occurred only by C. albicans, with no relevant differences when comparing mono and dual infection." (PMID 40284741, 2025). "Upon A-431 cells infection with G. vaginalis, the levels of IL-8, IL-1α, and IL-1β did not change, irrespective of the pretreatment or not with BL, even though a trend of increased IL-8 could be observed in BL-primed as compared to un-primed infected cells." (PMID 40384982, 2025). "Furthermore, after 24 but not 2 hr of infection, we observed a reduced release of the pro-inflammatory cytokine IL-1α from Tercko/ko T cells, suggesting a time-dependent reduction of T cell function." (PMID 39607755, 2024). "It has been reported that, after infection with G. parasuis, the expression of p38, ERK, and JNK increased in porcine alveolar macrophages (PAMs) via the NF-κB and MAPK signaling pathways, leading to the upregulation of inflammatory cytokines such as IL-1α, IL-1β, IL-6, IL-8, and TNF-α." (PMID 38927100, 2024). "Cytokines known as inappetence-inducing factors including IL-6, IL-1β, TNF, and IFN-g were not significantly different in the brain after infection, whereas IL-1α was significantly reduced (P < 0.0001) in the brain of both αCD8α treated and aIL-1a treated mice compared to RSV treated." (PMID 38382577, 2024). "Functionally, loss of IL-1rn in vivo biases HSC differentiation into the myeloid lineage and induces excess myeloid lineage expansion reminiscent of early hematological disease, through IL-1r1 and IL-1β overactivation in HSC but not IL-1α, in the absence of injury or infection." (PMID 36596811, 2023). "The infection of MDMs with Mtb opsonized with hSAA-1, compared to the infection with nonopsonized bacilli, led to at least a 2-fold increase in the concentrations of CSF2, CSF3, IL-1α, IL-1β, IL-6, IL-12, CCL15, and TNF-α with the most potent 10-fold increase observed for CCL5." (PMID 37781389, 2023). "RT-qPCR did not reveal significant differences in the amount of TMEV RNA as well as Ifnb1, Isg15, Eif2ak1 (PKR), Tnfa, Il1a, Il1b, Il6, Il10, Il12 (p40) and Ifng transcript numbers in the brain of Asc−/− and Casp1−/− mice and their respective wild type littermates at 4 days after TMEV infection." (PMID 37414913, 2023). "Hence, it plausible that with a less virulent infection, maternally‐derived IFNγ may be a more prominent driver of the HSC response, whereas with more virulent infections other cytokines, such as IL‐6 and IL‐1α, may further impact HSC function." (PMID 37259639, 2023). "Levels of six other chemokines and cytokines (IL-5, IL-1α, IL-3, G-CSF, IL-9, and eotaxin) were modestly increased or not increased with infection over time, but were reduced in basoIL-18R (−) mice relative to basoIL-18R (+) mice at 4 d PI (IL-5) or at 10 d PI (IL-1α, IL-3, G-CSF, IL-9, eotaxin)." (PMID 35985797, 2022). "Furthermore, knockdown of Nek7 significantly inhibited the secretion of IL-1β, but the secretion of IL-6, TNF-α, and IL-1α were not affected during PmCQ2 infection." (PMID 35350616, 2022). "Others, such as IL-1α, IL-2, IL-7, IL-9, IL-10, IL-12p40, IL-13, and VEGF were present at equivalent concentrations in lungs of infected and control mice during the first 5 days, but at significantly reduced concentrations in lungs of infected mice at day 7 post-infection." (PMID 35812400, 2022). "However, it is most likely the release of IL-1β, rather than IL-1α, associated with chemokine induction and neutrophil recruitment during GAS or S. aureus infection, as previously reported in other infection models involving bacterial pathogens." (PMID 33525468, 2021).
infection (continued). "Similarly, transcription of Il1α was greatly augmented to 66.5 ± 11.0 and 119.1 ± 11.4 counts in wild-type and Pdpn-TG cells post-infection, but not in Pdpn-KO cells." (PMID 34707599, 2021). "Subsequently, we sought to examine the influence of Ss infection on the systemic levels of Type-1 (IFN-γ, TNF-α, and IL-2), Type-17 (IL-17A and IL-22), Type-2 (IL-4, IL-5, and IL-13), regulatory (IL-10) and pro-inflammatory cytokines (IL-1α, IL-1β, IL-6, IL-12, and GM-CSF) in INF and UN individuals." (PMID 33042134, 2020). "PrimePCR array analysis of hNS/PCs showed that the mRNA levels of inflammatory cytokine related genes (IL-1A, TNFα, IL28A, IL29, NF-KB2), chemokines (CSF2, CCL3, CCL4, CXCR3),TLRs (TLR3, TLR8), IL-10, and Casp9 were all reduced in the Smaducin-6 treated group following ZIKV-FSS13025 infection." (PMID 32544190, 2020). "Secretion of proinflammatory mediators such as cytokines and chemokines (G-CSF, GM-CSF, IL-1α, IL1β, IL-6, IL-8, and CCL5) by epithelial cells, signal the recruitment of phagocytic cells, including neutrophils, macrophages and dendritic cells (DCs) to the site of infection." (PMID 31963180, 2020). "However, the systemic concentrations of some pro-inflammatory cytokines (IL-6 and CCL2), but not all (TNF-α, IL-1α, and IL-1β), were slightly over-induced in Ripk1LPC-KO mice at late stage of infection (72 hpi)." (PMID 30622241, 2019). "Thus, IL-1α values in infected groups were below the range in healthy animals (not statistically significant), and levels in the LDA group were lower than those obtained from the positive control group on days 14 and 28 post-infection." (PMID 29740435, 2018). "The increases in IL-1α observed later during infection in the spleens of BALB/c mice could indicate activation and secretion of IL-1α by inflammasome activation, though further data, such as caspase-1 activation and IL-18 expression would be required to validate this hypothesis." (PMID 30500862, 2018). "Unlike the lethal AG129 models, though, IL-1α decreased in response to D83-144 infection." (PMID 29559699, 2018). "The increased numbers of infiltrating leukocytes in infrabony lesions of anti-IL-1α/β-treated animals indicated that cell migration was not affected, and that infection dissemination may be explained by reduced phagocytic cell bactericidal activity." (PMID 28358036, 2017). "This indicates that neutrophil migration was not affected by anti-IL-1α/β blockade, suggesting that another function may have been compromised leading to a failure to localize infections." (PMID 28358036, 2017). "Importantly, several studies have shown that IL-1α and IL-1β can have non-redundant roles in infection and inflammation." (PMID 25629406, 2015). "Three of those genes, IL1A (interleukin 1 alpha), EDN1 (endothelin 1) and NFKB1 (nuclear factor of kappa light polypeptide gene enhancer in B-cells 1) were also found to be activated in pharyngeal and lung epithelial cell cultures in response to infection with Moraxella catarrhalis." (PMID 26125632, 2015). "We found that IL-1α protein levels were significantly decreased when CCR2+ monocytes were absent consistent with the idea that lung-resident CCR2+ inflammatory monocytes are important for producing and/or inducing expression of this cytokine in the lung at early times after infection." (PMID 25629406, 2015). "In addition, whilst intracellular IL-1α provoked cellular inflammatory responses, rather than behaving like a classical DAMP, IL-1α acted only when there was both infection and damage." (PMID 25395028, 2014). "Furthermore, Pkcδ-deficient macrophages produced higher amounts of IL-1α and CCL5, but not CXCL2 than WT macrophages in response to infection." (PMID 24516390, 2014). "J774.A1 cells, like RAW 264.7 cells, did not produce detectable IL1α until 24 h post infection." (PMID 25166426, 2014).